BRAF (B-Raf proto-oncogene, serine/threonine kinase)
Diseases named in the same sentence as BRAF in open-access papers (continued):
Sharing a sentence is not in itself a finding about the gene and the disease.
lung carcinoma (continued). "Clearly, the prognostic significance of BRAF mutations in lung cancer patients needs further elucidation." (PMID 33260892, 2020). "BRAFi combining MEKi has proved to be more effective than single-agents for BRAF V600E-mutated lung cancers." (PMID 32411601, 2020). "The multicenter retrospective EURAF cohort explored the efficacy of known BRAF inhibitors (vemurafenib, dabrafenib, or sorafenib) in BRAF-mutated lung cancer." (PMID 32411601, 2020). "We also detected the atypical lung cancer mutations BRAF (p.G469V) and ALK (p.R1275Q), whose clinical significance should be further evaluated." (PMID 32441866, 2020). "About 45.5% (5/11) of lung cancer patients with BRAF β3‐αC loop mutations demonstrated drug relevance." (PMID 32757330, 2020). "The most common BRAF mutation in lung cancer is the BRAF V600E mutation, accounting for roughly 50% of BRAF-mutant NSCLC." (PMID 31426419, 2019). "We observed that using the VE1 antibody for IHC analysis afforded highly sensitivity and specificity to detect BRAF V600E-mutated lung ADCs in tissues from primary lung cancer, metastatic tumors, or malignant pleural effusion cell blocks." (PMID 31234388, 2019). "While previous studies have shown that the prevalence of BRAF mutation in lung carcinoma is approximately 2-4%." (PMID 31781475, 2019). "In the present study, we validated the clinical application of IHC using the VE1 antibody to detect BRAF V600E-mutated lung ADCs from primary lung cancer, metastatic tumors, or malignant pleural effusion cell blocks." (PMID 31234388, 2019). "Next, we investigated classic lung cancer driver mutations that co-occur with BRAF mutations in this cohort." (PMID 31470866, 2019). "SSCP-PCR was performed for detection of V600E mutation in exon 15 of the BRAF gene from the lung carcinoma and normal lung tissue samples." (PMID 31781475, 2019). "A549 and H358 cell lines, which harbor KRAS G12S and G12C point mutations respectively, were used with normal lung fibroblast CCD19-Lu and a BRAF mutation lung cancer cell line, H1395, providing KRAS wild-type (WT) controls." (PMID 29440631, 2018). "This class of driver oncogenic BRAF mutations accounts for approximately half of the BRAF mutations in lung cancer." (PMID 29662630, 2018). "Publications focused on the possibility of detecting mutated protein such as EGFR, BRAF... directly on lung cancer tissue by mutation-specific IHC with 92% of sensitivity which is comparable to DNA sequencing." (PMID 30092812, 2018). "A total of 24 unique BRAF mutations including 4 novel ones were detected among 63 BRAF-mutated lung cancers." (PMID 29228562, 2017). "Until now, most clinical evidence was found in patients with glioblastoma and brain metastases and in patients with BRAF mutations, but some promising effects have been reported in patients with lung cancer, multiple myeloma and sarcoma as well." (PMID 29225688, 2017). "ctDNA also offers the possibility to detect acquired resistance mechanisms, including the second T790M mutation of EGFR, amplification of MET or HER2, and mutations of PIK3CA or BRAF, for early stage lung cancer patients under first-generation TKI medication." (PMID 28146051, 2017). "In contrast, the second-generation “paradox breaking” BRAFi (PLX8394), under clinical development, was found to successfully inhibit PLGG-associated BRAF-fusion and BRAF-mutant lung cancer." (PMID 29156677, 2017). "A recent vemurafenib BRAFV600E basket trial showed that 42% of lung cancers with the BRAF V600E mutation responded to vemurafenib." (PMID 28145866, 2017). "Till today, we have only limited data concerning the evaluation of the most frequent mutations in EGFR, KRAS, BRAF genes in CNS metastases of lung cancer (especially AC type)." (PMID 28097440, 2017). "Lung cancers with a non-V600 BRAF mutation are predicted to account for approximately 40,000 annual deaths worldwide." (PMID 28947956, 2017).
lung carcinoma (continued). "Dabrafenib (a selective BRAF inhibitor) alone or combined with trametinib (a MEK inhibitor) has shown efficacy in p.V600E-mutated lung cancers." (PMID 29228562, 2017). "Further studies are warranted to elucidate the clinical and/or biological significance of uncommon mutations, doublet non-p.L858R missense mutations of EGFR, and concomitant kinase-impaired BRAF mutations in lung cancers." (PMID 29228562, 2017). "ALK rearrangement, MET amplification, BRAF mutation which account for 3–7%, 2–4%, and 1–3%, respectively, represent less frequent alterations in lung cancer." (PMID 27485414, 2016). "Further analysis with the Mutagrator kinase mutation interpretation tool reveals that the mutated V855 residue also has positional homology to the lung cancer-derived BRAF- L597V kinase mutation." (PMID 26689995, 2016). "Responding to vemurafenib or dabrafenib has been observed in few NSCLC patients with a BRAF p.V600E mutation, although the exact benefit of selective BRAF inhibitors for lung cancer patients is currently still under investigation." (PMID 26498038, 2015). "A previous report demonstrated that the clinical outcomes of BRAF mutation-positive patients to platinum-based combination chemotherapy resembled those of wild-type lung cancer patients." (PMID 25621040, 2015). "BRAF mutations, although detected at lower frequencies in lung cancer, have emerged as an alternative important mechanism of MAPK signaling activation downstream of KRAS." (PMID 26208325, 2015). "V-Raf Murine Sarcoma Viral Oncogene Homolog B (BRAF) mutated lung cancer is relatively aggressive and is resistant to currently available therapies." (PMID 25706985, 2015). "Activating PIK3CA p.H1047R mutation has also been shown to cooperate with BRAF p.V600E mutation to promote progression of benign lung tumors to lung cancers." (PMID 26498038, 2015). "Trials on the use of dabrafenib in other solid tumors including BRAF V600E/K-mutatedcolorectal cancer, BRAF V600E-mutated non–small cell lung cancer, and BRAF V600E-mutated thyroidcancer are also ongoing." (PMID 25089220, 2014). "The majority of human lung cancers are adenocarcinomas carrying somatic mutations in the genes that encode the EGFR/KRAS/BRAF pathway." (PMID 22654667, 2012). "Bim has also been shown to mediate epidermal growth factor receptor (EGFR) inhibitor–induced apoptosis in lung cancer cells that have EGFR or BRAF mutations." (PMID 20885957, 2010). "That is, the smoking-gene interaction means that some smokers are at greater risk of developing lung cancer, with several host characteristics (i.e., K-ras, GSTM1, CYP2D6, c-MET, NKX2-1, LKB1, BRAF) implicated in lung cancer onset." (PMID 20843376, 2010). "Furthermore, due to the extremely low incidence of dMMR/MSI-H in lung cancer, especially in patients with BRAF V600E mutations, evidence supporting the predictive value of dMMR/MSI-H for immunotherapy in this population is limited." (PMID 41480531, 2025). "In the current study, we evaluate a multi-institutional cohort of lung cancer patients with all classes of BRAF mutation receiving chemotherapy, immunotherapy, or targeted therapy to evaluate treatment efficacy for each class of BRAF mutation." (PMID 41152458, 2025). "To establish the mechanism of action (MOA) by which exarafenib could exert anti-tumor effects in human cancer cells, we conducted a series of experiments using patient-derived lung cancer cell lines harboring BRAF mutations." (PMID 41282105, 2025). "Between Oct 2017 and Dec 2023, 129 BRAF-mutated lung cancer patients were identified." (PMID 40242250, 2025). "A variety of targeted therapies have achieved good efficacy in lung cancers with BRAF mutations." (PMID 39529955, 2024). "However, there are no reports of clinical trials for cases with poor PS in v-Raf murine sarcoma viral oncogene homolog B (BRAF) gene mutated lung cancer." (PMID 39759653, 2024). "BRAF V600E mutation is also an acquired resistance mechanism in lung cancer." (PMID 39139611, 2024).
lung carcinoma (continued). "Slightly more prevalent than in lung cancer, BRAF mutations are found in about 10% of CRCs." (PMID 38539548, 2024). "In other words, the investigation of KRAS mutation in lung cancer, prognosis evaluation for patients with BRAF or RAS mutations, and elucidation of EGFR’s role in NSCLC and lung adenocarcinoma represent pivotal research directions within this field that have made significant advancements." (PMID 38706597, 2024). "The meta-analysis unveiled a noteworthy correlation between BRAF mutation and lung cancer." (PMID 38394545, 2024). "In addition, mutations in the RAS and BRAF genes have been found to mediate TKI-induced drug resistance during lung cancer therapy." (PMID 36918558, 2023). "Known lung cancer-associated fusions, including BRAF and RET, were also identified." (PMID 36675685, 2022). "The prognostic role of BRAF V600E mutation in lung cancer is still unclear." (PMID 35454926, 2022). "Also, BRAF mutation, another different lung cancer driver mutation, is frequent in smoking patients." (PMID 35991047, 2022). "Many BRAF mutations (G469A, V600E, and V599E) have been found in cancer, including lung cancer." (PMID 35840984, 2022). "Currently, Dabrafenib and Trametinib are recommended for patients with a BRAF-V600E mutation, which was the only mutation detected in all the 28 cases (3% of the total tested) in our series; this will surely improve the prognostic role of BRAF mutations in lung cancer in the future." (PMID 35012520, 2022). "Moreover, the treatment of BRAF-mutated lung cancer with ICIs showed some efficacy, reflecting high PD-L1 expression and TMB." (PMID 35407463, 2022). "Similarly, a highly sensitive and specific RT-qPCR method has been developed for screening BRAF V600E/K mutation, which frequently occurs in lung cancers." (PMID 36553654, 2022). "In lung cancer, BRAF is mutated in approximately 2–4% of cases." (PMID 35454926, 2022). "BRAF V600E-mutated lung cancer has aggressive characteristics and is resistant to chemotherapies." (PMID 34484797, 2021). "In NSCLC, the incidence of BRAF mutations is low, accounting for 0–3% of all cases of lung cancer." (PMID 33474634, 2021). "Activation of MAPK signaling via BRAF mutations may limit the activity of EGFR inhibitors in EGFR-mutant lung cancer patients." (PMID 34921211, 2021). "In summary, a highly sensitive and BRAF V600E/K mutation-specific RT-qPCR was established for detection of BRAF V600E/K mutation and results found low incidence of the BRAF V600E mutation in the lung cancer population of southern Taiwan." (PMID 33037234, 2020). "Only two BRAF V600E mutation cases were identified from the studied lung cancer population; hence, the performance of the developed RT-qPCR assay and V600E-specific immunohistochemistry could not be well validated." (PMID 33037234, 2020). "Tumors with mutations in BRAF (7% of lung cancers) may be treated with vemurafenib or dabrafenib, and tumors with rearrangements involving ALK and/or ROS1 (1–2% of lung cancers) may be treated with crizotinib, ceritinib or alectinib." (PMID 32898185, 2020). "Reported incidences of BRAF mutations in lung cancers ranged from 0.9 to 8.9%." (PMID 33037234, 2020). "The incidence of BRAF V600E mutation in the studied lung cancer population was 0.65%." (PMID 33037234, 2020). "BRAF directed therapy, dabrafenib plus trametinib is now approved for treatmentlung cancer patients where BRAF mutations are noted in about 2–4% of patients, however, their utility in lung cancer with brain metastases is yet to be evaluated." (PMID 30886831, 2019). "To study whether BRAF V600 mutations in non–small-cell lung cancer (NSCLC) may indicate sensitivity to the BRAF inhibitor vemurafenib, we included a cohort of patients with NSCLC in the vemurafenib basket (VE-BASKET) study." (PMID 32914022, 2019).
lung carcinoma (continued). "A large fraction of somatic driver BRAF mutations in lung cancer are non-V600 and impaired-kinase." (PMID 29662630, 2018). "BRAF mutated lung cancer is a genetically distinct subtype that accounts for about 5% of NSCLC." (PMID 29484121, 2018). "Importantly, advanced lung cancer patients with non-V600 BRAF mutation has worse overall survival than V600E mutant patients." (PMID 29739364, 2018). "A lung carcinoma cell line harboring the v-Ki-ras2 Kirstej rat sarcoma viral oncogene homolog and other cell line containing an activating V600E mutation in v-raf-murine sarcoma viral oncogene homolog B1 (BRAF) were moderately sensitive to erastin." (PMID 28168164, 2017). "ATM loss also enhances the sensitivity of KRAS- or BRAF-mutant lung cancer cells to MEK inhibition." (PMID 27922010, 2016). "Interestingly, the frequency of BRAF mutations in primary lung cancer is higher – an overview reported that 36 out of 883 NSCLCs had BRAF V600E mutations." (PMID 27350555, 2016). "Another possible implication for the future of precision medicine is that even if newer targeted therapy for BRAF or KRAS mutations was successfully introduced for lung cancer, it may treat only the more aggressive subtype in some tumors." (PMID 24742923, 2014). "However, despite the lower frequency of Class I mutations in lung cancer compared to other malignancies, lung cancer represented the largest number of patients with BRAF alterations across all cancers surveyed, given the large of number of patients diagnosed annually." (PMID 41282105, 2025). "Finally, we included 10 well-known cancer-related genes (or their hotspot-containing exons) listed as most frequently mutated in lung cancer (BRAF,EGFR,ERBB2,HRAS,KRAS,MAP2K1,MET,NF1,NRAS, and RIT1) in the panel to serve as internal controls for highly mutated regions." (PMID 40867048, 2025). "This indicates that re-activating this kinase using adenovirus-based therapy could be used to treat this type of cancer in combination with classical drugs used in lung cancer presenting BRAF mutations, such as BRAF or MEK inhibitors, dabrafenib, or trametinib." (PMID 36678835, 2023). "Taken together, these findings suggest that the heightened activation of YAP, as observed in EGFR- or KRAS-mutated lung adenocarcinoma, as well as BRAF-mutant lung cancer cells and KRAS-mutant NSCLC tumors, might play a significant role in conferring resistance to MEK inhibition." (PMID 37569866, 2023). "Those low frequencies of ALK rearrangement and BRAF mutations could be attributed to the type of samples in our study, as we only have surgical resection samples and most of the patients were at early stages of lung cancer." (PMID 33956842, 2021). "However, 50–80% of BRAF mutations in lung cancer are non-V600, and can be class II, with intermediate to high kinase activity and RAS independence, or class III, with impaired kinase activity, upstream signaling dependence, and consequently, sensitivity to receptor tyrosine kinase (RTK) inhibitors." (PMID 31533235, 2019). "However, BRAF mutations are detected only in 1–2% of lung cancer patients." (PMID 21124782, 2010). "BRAF mutations are the most prevalent among the three RAF isoforms, occurring in 1.5–3.5% of lung cancer cases." (PMID 40647542, 2025). "For instance, mutations in the BRAF gene, which encodes a serine/threonine kinase involved in the MAPK signaling pathway, have been detected in a subset of radon-induced lung cancers." (PMID 40427695, 2025). "In lung cancer, particularly non-small cell lung cancer (NSCLC), oncogenic alterations such as mutations in KRAS, EGFR, BRAF, and ALK rearrangements activate key signaling cascades, most notably the RAS–RAF–MEK–ERK and PI3K-AKT–mTOR pathways." (PMID 40823246, 2025). "Given its promising in vitro activity, exarafenib was advanced into in vivo studies focusing on lung cancer, using cell line-derived xenograft (CDX) and patient-derived xenograft (PDX) models of BRAF-mutated human cancers." (PMID 41282105, 2025).